OR12D2 (olfactory receptor family 12 subfamily D member 2)
Description:
Odorant receptor.
Synonyms: hs6M1-20; DJ994E9.8
Tractability: Antibody: UniProt places it where antibodies can reach, with medium confidence; UniProt predicts a signal peptide or a membrane-spanning region; its Gene Ontology location is reachable by antibodies, with medium confidence. PROTAC: ubiquitination databases record sites on it.
Gene: Protein-coding gene on chromosome 6 (29,395,631 to 29,398,008, forward strand). Ensembl gene ENSG00000280236.
Subcellular location: Cell membrane
Pathways (Reactome):
Sensory Perception: Expression and translocation of olfactory receptors
Gene Ontology:
Molecular function: odorant binding; olfactory receptor activity; G protein-coupled receptor activity
Biological process: detection of chemical stimulus involved in sensory perception of smell; G protein-coupled receptor signaling pathway
Cellular component: membrane; plasma membrane
Genetic constraint (gnomAD): Loss-of-function variants: 0 observed, 0.0866 expected, observed/expected ratio (o/e) 0, 90% interval 0 to 1.89. That is too few expected variants to judge how well the gene tolerates losing a copy. Missense variants: 345 observed, 387.76 expected, observed/expected ratio (o/e) 0.89, 90% interval 0.81 to 0.97. Synonymous variants: 146 observed, 148.84 expected, observed/expected ratio (o/e) 0.98, 90% interval 0.86 to 1.12.
Homologues: Paralogues in human: OR12D3 (66% identical), OR12D1 (63% identical), OR1E1 (44% identical), OR1E2 (44% identical), OR1L1 (44% identical), OR1L4 (44% identical), OR4S2 (44% identical), OR1L3 (43% identical), OR4A15 (43% identical), OR7D2 (43% identical), OR1L6 (43% identical), OR4C15 (43% identical), and 116 more.
Diseases named in the same sentence as OR12D2 in open-access papers:
OR12D2 is named in the same sentence as 7 diseases in open-access papers, as found by Europe PMC text mining. Sharing a sentence is not in itself a finding about the gene and the disease. The quoted sentences say what the papers report.
autism (1 paper, 2022). Persistent deficits in social interaction and communication and interaction as well as a markedly restricted repertoire of activity and interest as well as repetitive patterns of behavior. "Unlike previous results, our study identified a single gene, OR12D2 (including up and downstream; NC_000006.11:g.29360183-g.29369519), with 10 common SNPs and large effects on risk in patients with autism." (PMID 35215271, 2022). "The olfactory receptor genes OR12D2 and OR5V1, which are involved in the olfactory signaling pathway, G alpha (s) signaling events, GPCR downstream signaling, and GPCR signaling and signal transduction together regulate the overall olfactory growth, behavior, and impairment associated with autism." (PMID 35215271, 2022).
psoriasis (1 paper, 2011). An autoimmune condition characterized by red, well-delineated plaques with silvery scales that are usually on the extensor surfaces and scalp. "In addition to classical HLA genes such as HLA-C, HLA-B and HLA-DQA2, we also find association of non-HLA genes in the MHC region such as POU5F1, NFKBIL1, NOTCH4, MICA, IER3 and OR12D2 with psoriasis." (PMID 22125590, 2011). "In addition, we found that SNPs from several non-HLA genes including rs2251396, rs2523454 and rs12175589 in MICA, rs7770216 in LOC729816, rs511027 in NOTCH4, rs9257483 in OR12D2 and 9262167 in IER3 were associated with psoriasis in multiple regression analyses." (PMID 22125590, 2011).
OR12D2 also shares sentences with these, for which no sentence is quoted: amyotrophic lateral sclerosis (1 paper); autism spectrum disorder (1); mastitis (1); schizophrenia (1); systemic lupus erythematosus disease (1).